NOL12 (nucleolar protein 12)
Description:
Multifunctional RNA binding protein that plays a role in RNA metabolism and DNA maintenance. Participates in the resolution of DNA stress and the maintenance of genome integrity by localizing to sites of DNA insults. Also plays a role in proper nucleolar organization by limiting nucleolar size and regulating nucleolar number. Mechanistically, regulates the nucleolar levels of fibrillarin and nucleolin, two key players in pre-rRNA processing and ribosome assembly.
Synonyms: MGC3731; Nop25; RRP17; VITO; dJ37E16.7
Tractability: PROTAC: ubiquitination databases record sites on it.
Gene: Protein-coding gene on chromosome 22 (37,681,673 to 37,693,476, forward strand). Ensembl gene ENSG00000273899.
Subcellular location: Nucleus, nucleolus; Nucleus; Cytoplasm
Subcellular location (Human Protein Atlas): Mitotic chromosome; Nucleoli; Nucleoplasm; Vesicles
Pathways (Reactome):
Metabolism of RNA: Major pathway of rRNA processing in the nucleolus and cytosol
Gene Ontology:
Molecular function: identical protein binding; protein binding; RNA binding; rRNA binding; single-stranded DNA binding
Cellular component: cytoplasm; nucleus; nucleolus
Genetic constraint (gnomAD): Loss-of-function variants: 20 observed, 21.23 expected, observed/expected ratio (o/e) 0.94, 90% interval 0.66 to 1.37. The upper end of that interval is the gene's LOEUF score, 1.37, which puts it in group 5 of 6, group 1 being the genes least tolerant of losing a copy. Missense variants: 283 observed, 279.8 expected, observed/expected ratio (o/e) 1.01, 90% interval 0.92 to 1.12. Synonymous variants: 133 observed, 112.78 expected, observed/expected ratio (o/e) 1.18, 90% interval 1.02 to 1.36.
Homologues: Orthologues: chimpanzee NOL12 (99% identical), dog NOL12 (93% identical), mouse Nol12 (91% identical), guinea pig NOL12 (90% identical), rabbit NOL12 (88% identical), macaque NOL12 (84% identical), rat Nol12 (80% identical), pig NOL12 (64% identical), tropical clawed frog nol12 (58% identical), zebrafish nol12 (50% identical).
Diseases named in the same sentence as NOL12 in open-access papers:
NOL12 is named in the same sentence as 8 diseases in open-access papers, as found by Europe PMC text mining. Sharing a sentence is not in itself a finding about the gene and the disease. The quoted sentences say what the papers report.
hepatocellular carcinoma (2 papers, 2022). A malignant tumor that arises from hepatocytes. "However, whether NOL12 promotes the progression of hepatocellular carcinoma, whether it affects the immune infiltration of HCC, and whether it can be used as a predictor of ICIs therapy have not been reported." (PMID 35693698, 2022). "NOL12 expression is reportedly upregulated in hepatocellular carcinoma (HCC) tissues and cells and correlates with a short OS." (PMID 36338724, 2022).
HIV-1 infection (1 paper, 2024). The type species of lentivirus and the etiologic agent of acquired immunodeficiency syndrome (AIDS). "NOL12 encodes an RNA-binding protein that plays an important role in repairing DNA damage pathways and maintaining genome integrity, although its effect on HIV-1 infection remains unclear (log2FC = −0.59)." (PMID 39066239, 2024).
retinoblastoma (1 paper, 2024). A malignant tumor that originates in the nuclear layer of the retina. "The expression of NOL12 in the WERI-Rb1 cell, a human retinoblastoma cell line, was also examined using RT-PCR, Western blotting, and immunofluorescent staining." (PMID 38467618, 2024). "In the human retinoblastoma cell line WERI-Rb1, we found that altering NOL12 expression led to a change in WERI-Rb1 cell viability." (PMID 38467618, 2024).
tumor (3 papers, 2020 to 2024). "In addition, KEGG analysis also showed that NOL12 was associated with a variety of tumor-related signaling pathways, including the MAPK, PI3K-Akt, cAMP, and Ras signaling pathways." (PMID 35693698, 2022). "The second cluster (rightmost group) includes relevant cancer types such as COAD or READ and shares the enrichment of PABPN1 and NOL12, both of which are related to tumor progression." (PMID 39595158, 2024). "CIBERSORTx analysis revealed that twelve types of tumor-infiltrating immune cells (TICs) are correlated with NOL12 expression." (PMID 35693698, 2022). "Second, through CIBERSORTx and functional enrichment analysis, we found that NOL12 is related to a variety of TICs and tumor-related signaling pathways." (PMID 35693698, 2022). "The results showed that only one tumor metastasis was observed in the lungs of the mice in the NOL12-knockdown group (1/6), while lung metastases were observed in each mouse in the shCtrl group (6/6)." (PMID 35693698, 2022). "To further confirm the tumor-promoting effect of NOL12 in HCC, we carried out a series of experiments in vitro and in vivo." (PMID 35693698, 2022). "Together, these findings suggested that knockdown of NOL12 significantly inhibited the growth of HCC cells in vitro and their tumor formation ability in vivo." (PMID 35693698, 2022). "The results indicated that, as NOL12, PABPC1L, RNASE2, RPL22L1, and OASL expression increased, tumor grade, AJCC stage, T stage, and M stage in KIRC patients increased." (PMID 33229623, 2020). "NOL12, PABPC1L, RNASE2, RPL22L1, OASL, and YBX3 expression were significantly positively correlated with tumor grade and AJCC stage, while RBM47 expression was negatively correlated with tumor grade and AJCC stage." (PMID 33229623, 2020).
cancer (2 papers, 2020 to 2024). A tumor composed of atypical neoplastic, often pleomorphic cells that invade other tissues.
infection (1 paper, 2023). The state of being infected such as from the introduction of a foreign agent such as serum, vaccine, antigenic substance or organism. "In our experiment, bacterial growth assessed after 72 h post infection (hpi) showed significantly higher pathogen multiplication in the nol12-4 mutants compared to the WT plants, which indicates that plants lacking AtNOL12 are more sensitive to Pst." (PMID 37919659, 2023).
NOL12 also shares sentences with these, for which no sentence is quoted: Seckel syndrome (1 paper); Werner syndrome (1).